SOX2 (SRY-box transcription factor 2)
Diseases named in the same sentence as SOX2 in open-access papers (continued):
Sharing a sentence is not in itself a finding about the gene and the disease.
Gonadotropin deficiency (3 papers, 2018 to 2021). A reduced ability to secrete gonadotropins, which are protein hormones secreted by gonadotrope cells of the anterior pituitary gland, including the hormones follitropin (FSH) and luteinizing hormone (LH). "Selective gonadotropin deficiency as a result of SOX2 mutation, which spares other hormones of the hypothalamic-pituitary axis, has been described in the literature." (PMID 34948037, 2021).
HCMV infection (3 papers, 2013 to 2024). "While expression of the NSPC markers Sox2 and Pax6 were kept at high levels following HCMV infection, that of another NSPC marker Nestin was markedly suppressed at 7 dpi." (PMID 24144363, 2013). "This positive feedback loop may lead to a potentially synergetic tumor-promoting effect from SOX2 and HCMV infection." (PMID 37058447, 2023). "Importantly, this phenotype can be rescued by overexpressing PML, confirming the direct participation of the SOX2-PML axis in regulating HCMV infection." (PMID 37058447, 2023). "Notably, the impact of the regulation of the SOX2-PML axis on HCMV infection and its oncomodulatory activities were then demonstrated in a patient-derived xenograft (PDX) mouse model." (PMID 37058447, 2023). "Upon HCMV infection, SOX2-positive cells were more susceptible than SOX2-negative cells, as indicated by viral IE1 expression." (PMID 37058447, 2023). "Next, we studied the impact of SOX2 overexpression (OE) and knockout (KO) on HCMV infection." (PMID 37058447, 2023). "In addition, SOX2-OE enhanced the oncomodulatory activities of HCMV infection, which could be offset by induced PML expression." (PMID 37058447, 2023).
Hydrocephalus (3 papers, 2013 to 2014). Hydrocephalus is an active distension of the ventricular system of the brain resulting from inadequate passage of CSF from its point of production within the cerebral ventricles to its point of absorption into the systemic circulation. "The first description identified a SOX2 missense mutation in two children (anophthalmia/cryptophthalmos, severe hydrocephalus, and corpus callosum agenesis in a terminated fetus and BA in one sibling)." (PMID 24498598, 2013). "Thus, disruption of Sox2 function in the embryonic head region could be an additional cause for the development of hydrocephalus later on in life." (PMID 25309446, 2014). "Neural-specific Sox2 excision results in enlarged lateral ventricles ∼E19.5 due to decreased proliferation of neural stem and progenitor cells, suggesting that hydrocephalus in Sox2COND MUT embryos may result from insufficient expansion/thickening of the neuroepithelium." (PMID 24244203, 2013).
Hyperglycemia (3 papers, 2023 to 2025). An increased concentration of glucose in the blood.
hypopharyngeal cancer (3 papers, 2018 to 2020). Carcinoma, predominantly squamous cell, arising from the epithelial cells of the hypopharynx. "Comparing tumour sites revealed that 30.14%, 32.88%, 30.68%, and 6.30% of patients in the SOX2-high subgroup had oral cavity cancer, oropharynx cancer, larynx cancer, and hypopharynx cancer, respectively; and that 67.99% of patients in the SOX2-low subgroup had oral cavity cancer." (PMID 29374236, 2018). "Furthermore, the absence of SOX2 expression was associated with poor esophageal and hypopharyngeal cancer prognosis." (PMID 32098209, 2020). "Moreover, in esophageal and hypopharyngeal cancer, the absence of SOX2 expression was associated with poor prognosis." (PMID 30867047, 2019).
influenza (3 papers, 2019 to 2025). An acute viral infection of the respiratory tract, occurring in isolated cases, in epidemics, or in pandemics; it is caused by serologically different strains of viruses (influenzaviruses) designated A, B, and C, has a 3-day incubation period, and usually lasts for 3 to 10 days. "Loss of Sox2 expression leads to a loss of airway cell identity at homeostasis and enhances airway cell fate reprogramming into both alveolar epithelial cells and keratinized Trp63+ cells following influenza infection." (PMID 38182591, 2024). "At 24 hpi, we obtained similar results; decreased expression of Oct4 and Sox2 after influenza-induced autophagy." (PMID 31000695, 2019). "scRNA-seq analysis at 28 days after influenza infection shows that Sox2 lineage-traced cells can generate bona fide AT2 cells, as indicated by expression of canonical AT2 markers such as Sftpc and Lamp3, but with very low levels of secretory cell markers such as Scgb1a1." (PMID 38182591, 2024). "Moreover, using multiple lineage tracing strategies, Sox2+ lineage‐negative progenitor cells were shown to be the main source of emerging Krt5+ cells in influenza‐induced lung injury, whereas Sox2+Krt5+ resident basal cells made a significantly minor contribution." (PMID 41318981, 2025). "There was no functional benefit of Sox2 pan-airway knockout for influenza infection; however, basaloid progenitor-specific Sox2 activation could theoretically be beneficial to promote functional regeneration in response to alveolar injury." (PMID 38182591, 2024).
intraepithelial neoplasia (3 papers, 2021 to 2026). A precancerous neoplastic process that affects the squamous, glandular, or transitional cell epithelium without evidence of invasion. "Immunohistochemistry (IHC) was used to identify stem cell biomarkers in tissue samples, most studies demonstrated that higher expression of stem cell markers (CD44, ALDH1, HELLS, TARIF, SOX2, NANOG, and CD147) correlated with severity of epithelial dysplasia." (PMID 41778103, 2026).
Miscarriage (3 papers, 2024 to 2025). A pregnancy that ends at a stage in which the fetus is incapable of surviving on its own, defined as the spontaneous loss of a fetus before the 22th week of pregnancy.
myopia (3 papers, 2023 to 2024). "In contrast, among all IHH patients with missense SOX2 variants, only 1 displayed mild eye defects (myopia and small palpebral fissures) (case 3)." (PMID 36602867, 2023). "The SOX2 gene’s rs4575941 allele G, which may be a risk gene for high myopia in the Chinese population, was predicted to play some roles in the genetic vulnerability to high myopia." (PMID 37740201, 2023). "Researchers indicate that PAX6 rs644242, ZC3H11B rs4373767 and BICC1 rs7084402, VIPR2 rs885863 and rs6979985, ZMAT4 rs7829127, TNKS rs4840437 and rs6989782, PDGFRA rs2114039, SOX2 rs4575941, FGF10 rs339501, rs2973644, and rs 79002828 are associated with severe myopia (moderate and extreme myopia)." (PMID 38660258, 2024).
non-small cell lung adenocarcinoma (3 papers, 2018 to 2024). Type of epithelial lung cancer arising from glandular origin. "Here we demonstrate that nicotine can induce the expression of embryonic stem cell factor Sox2, which is indispensable for self-renewal and maintenance of stem cell properties in non-small cell lung adenocarcinoma (NSCLC) cells." (PMID 30322398, 2018).
NUT carcinoma (3 papers, 2021 to 2026). "BRD4::NUTM1 has been shown to drive overexpression of SOX2 in NUT carcinoma cells, which induces an aberrant stem cell-like growth feature." (PMID 38315310, 2024). "NUT carcinomas show frequent reactivity to epithelial markers (various cytokeratins and rarely Claudin-4), SOX2, and MYC antibodies." (PMID 34898574, 2021). "This study shows that SOX2 is not required for NUT carcinoma initiation or maintenance in vivo, challenging its assumed oncogenic role and refining therapeutic target prioritization." (PMID 41266112, 2026). "NUT carcinoma is primarily considered an epigenetically driven cancer in which the BRD4–NUT–p300 axis promotes widespread chromatin hyperacetylation and activates the expression of SOX2, MYC, TP63, and likely other transcription factors to drive NC tumorigenesis and SCC phenotype." (PMID 41266112, 2026). "However, SOX2 and MYC are not specific stains for NUT carcinoma." (PMID 34898574, 2021).
oral cavity cancer (3 papers, 2018 to 2025). A primary or metastatic malignant neoplasm involving the oral cavity. "In this study, one of the mechanisms underlying the poor prognosis of lower SOX2 IHC scores was that lower SOX2 scores were associated with advanced T classification (pT3 and -4), which was similar to other studies on oral cavity cancer." (PMID 33182283, 2020). "The relation to SOX2 expression and potential impact of epigenetic regulation thus appears to play an important role regarding the overall survival of patients with oral cavity carcinoma." (PMID 39180200, 2025).
Oropharyngeal Cancer (3 papers, 2018 to 2021). Carcinoma, predominantly squamous cell, arising from the epithelial cells of the oropharynx. "Consistent with our results, SOX2 was proven to be a potential marker to predict overall survival and recurrence in p16+ oropharyngeal cancer." (PMID 33789601, 2021). "Because RT-related outcome was known to be worse in p16− oropharyngeal cancer than p16+, SOX2 needs to be further investigated as a candidate prognosticator to precisely select RT as a treatment option, especially in p16− OPSCC." (PMID 33182283, 2020). "Therefore, the purpose of the study was to analyze the implication of SOX2 in oropharyngeal cancer as the next available marker following p16 and to validate our results in the TCGA-HNSC dataset." (PMID 33182283, 2020). "Three markers, PD-1, PD-L1 and CTLA-4, related to immune therapy were not significantly different according to SOX2 expression in either HPV+ or HPV− oropharyngeal cancers (all p > 0.05)." (PMID 33182283, 2020).
oropharyngeal squamous cell carcinomas (3 papers, 2014 to 2023). "Finally, similar to the HPV cohort of oropharyngeal squamous cell carcinomas, SOX2 abundance and NRF2 activity trended to a positive correlation." (PMID 37716475, 2023).
osteoarthritis (3 papers, 2016 to 2022). A noninflammatory degenerative joint disease occurring chiefly in older persons, characterized by degeneration of the articular cartilage, hypertrophy of bone at the margins and changes in the synovial membrane. "In another study of fast- and slow-growing subsets of hBM-MSCs from osteoarthritis patients, genes encoding sex-determining region Y-box 2 (SOX2), notch homolog 1 (NOTCH1), and the notch ligand delta-like 3 (DLL3) were among the upregulated genes in fast-growing MSCs." (PMID 31636675, 2019). "Fibroblast-like synoviocytes (FLSs) of patients with RA (n = 3) and osteoarthritis (OA) (n = 3) and dermal fibroblasts of healthy subjects (n = 3) were efficiently reprogrammed by lentiviral transduction of oct4, sox2, nanog and c-myc." (PMID 27609119, 2016).
Parkinson disease (3 papers, 2013 to 2022). A progressive degenerative disorder of the central nervous system characterized by loss of dopamine producing neurons in the substantia nigra and the presence of Lewy bodies in the substantia nigra and locus coeruleus. "In this study, we have analyzed the expression of Sox-2 in the nigrostriatal system in macaques (Macaca fascicularis), to examine their presence in these structures, their capability to generate new neurons and their response to neurotoxicity and dopamine loss in a model of Parkinson's disease." (PMID 23824751, 2013). "The number of SOX-2- and nestin-expressing cells is also reported to be reduced in the dentate gyrus of Parkinson’s disease patients with dementia." (PMID 31980673, 2020). "Elucidating the signals and factors that regulate fate decisions in Sox-2+ striatal progenitor cells can pave the way for endogenous restoration of dopamine transmission in Parkinson's disease." (PMID 23824751, 2013). "Given their potential capacity to differentiate into neurons and their responsiveness to dopamine neurotoxic insults, striatal Sox-2+ cells represent good candidates to harness endogenous repair mechanisms for regenerative approaches in Parkinson's disease." (PMID 23824751, 2013).
rectal cancer (3 papers, 2017 to 2018). A primary or metastatic malignant neoplasm that affects the rectum. "Previous studies have reported that SOX2 overexpression increases the radioresistance of cervical SCC, rectal cancer, and glioblastoma." (PMID 29374236, 2018).
schwannoma (3 papers, 2023 to 2025). A benign, usually encapsulated slow growing tumor composed of Schwann cells. "Chemical induction of RKIP can degrade SOX2, inhibit tumour growth and promote differentiation of schwannoma into mature Schwann cells." (PMID 37963558, 2023). "Schwannoma cells show upregulation of stem cell markers such as SOX2, CD133, and OCT4." (PMID 38945076, 2024).
Sepsis (3 papers, 2020 to 2026). Sepsis is defined as life-threatening organ dysfunction caused by a dysregulated host response to infection. "We evaluated the expression levels of several lncRNAs implicated in sepsis progression, including growth arrest‐specific 5 (Gas5), the RNA component of mitochondrial Rmrp, and SOX2 overlapping transcript (Sox2ot), in AEC‐IIs and their derived exosomes." (PMID 41178622, 2026). "Inhibiting SOX2OT/SOX2 signaling may be effective for treating or preventing neurodegeneration in sepsis-associated encephalopathy." (PMID 33100215, 2020). "SOX2OT knockdown improves sepsis-induced deficits in hippocampal neurogenesis and cognitive function by downregulating SOX2 in mice." (PMID 33100215, 2020). "SOX2OT knockdown attenuated sepsis-induced neurogenesis impairment and cognitive dysfunction, likely through its effects on downstream SOX2 signaling." (PMID 33100215, 2020). "Furthermore, our data suggest that sepsis upregulates the transcription factor OCT4 through the SOX2OT/SOX2 axis." (PMID 33100215, 2020). "Moreover, we found that SOX2 knockdown reduced sepsis-induced hippocampal neurogenesis and cognitive dysfunction, similar to the beneficial effects of SOX2OT knockdown." (PMID 33100215, 2020). "We also asked whether knocking down SOX2OT may ameliorate these sepsis-induced effects by downregulating SOX2." (PMID 33100215, 2020). "First, our data demonstrated that sepsis induced by CLP surgery led to cognitive dysfunction and upregulation of SOX2OT and SOX2." (PMID 33100215, 2020).
testicular cancer (3 papers, 2011 to 2024). A primary or metastatic malignant neoplasm that affects the testis. "For example, SOX2, NANOG and LIN28 expression can be used to distinguish different histological subtypes of human testicular cancers." (PMID 21851623, 2011). "Almost all of the top-performing genes were that of over-expression, with PMS2 in THYM; CARD11, LASP1, STIL, POLE, KMT2C, and CLIP1 in testis cancer; ERC1, WRN, OLIG2, FANCC, and ACSL6 in ACC; and SOX2 and NDRG1 in ESCA leading in performance with AUCs ranging 0.832-0.911." (PMID 38491101, 2024).
thymoma (3 papers, 2019 to 2025). A neoplasm arising from the epithelial cells of the thymus. "Interestingly, the mRNA expression of SOX2 in fresh tumor tissues from thymic carcinomas was significantly higher than that observed in thymomas." (PMID 38201593, 2023). "By the ssGSEA method, we proved that CTNNB1, EGFR, SOX2, and ERBB2 expressions showed significant correlation with Th17 T cell in thymoma, and KEGG analysis suggested that differential genes were highly enriched in the IL-17 pathway." (PMID 39192657, 2025). "Higher expressions of SOX2 and IGF-1 proteins were markedly elevated in thymic carcinomas compared to thymomas, as observed through immunohistochemistry." (PMID 38201593, 2023). "CTNNB1, EGFR, SOX2, and ERBB2 expressions revealed a significant correlation with NK cells in thymoma, and these four genes may play a role in regulating NK cells in TAMG." (PMID 39192657, 2025).
ulcerative colitis (3 papers, 2017 to 2024). An inflammatory bowel disease involving the mucosal surface of the large intestine and rectum. "Sox2 expression was investigated in colonic neurons of human patients with Clostridium difficile or ulcerative colitis." (PMID 28566702, 2017).
acute leukemia (2 papers, 2024 to 2025). A clonal (malignant) hematopoietic disorder with an acute onset, affecting the bone marrow and the peripheral blood. "BAALC binder of MAP3K1 and KLF4 (BAALC), a regulator of developing neuroectoderm tissues overexpressed in acute leukemia and GBM, and a target of SOX2 in differentiated GBM cells, was upregulated in HF2303 SDCs." (PMID 39919036, 2025). "Also, both SOX2 and OCT3/4 might be a therapeutic target, especially in resistant acute leukemia." (PMID 38342816, 2024).
alcohol dependence (2 papers, 2017 to 2021). Physical and psychological dependence on alcohol. "Following 7 days of abstinence from alcohol dependence, we observed a striking fourfold increase in NPC proliferation (BrdU+ and Ki67+), which is likely due to an increase in active cycling of NPCs (Sox2+ /Ki67+)." (PMID 34594180, 2021). "Next, we examined NPC activation by quantifying the number of Ki67 and Sox2 co-labeled cells, as we observed an increase in activated NPCs in the SGZ of males following alcohol dependence." (PMID 34594180, 2021). "We observed an increase in the number of cells colabeled for Sox2 and BrdU in the SGZ in the ethanol group as compared to controls, which supports that prior alcohol dependence results in an increase in the number of proliferating NPCs." (PMID 29326611, 2017).
Anaplastic Thyroid Carcinoma (2 papers, 2015 to 2021). "Anaplastic thyroid carcinoma (ATC) has characteristics suggestive of a tumour enriched in CSC.Previous studies suggested that the stem cell factor SOX2 has a preeminent hierarchical role in determining the characteristics of stem cells in SW1736 ATC cell line." (PMID 25705224, 2015). "Here we report that inhibition of the Shh pathway by Gli1 siRNA or by cyclopamine and GANT61 reduced BMI1 and SOX2 expression in SW1736 and KAT-18 cells, two anaplastic thyroid cancer cell lines." (PMID 33499351, 2021).
anemia (2 papers, 2015 to 2022). A reduction in the number of red blood cells, the amount of hemoglobin, and/or the volume of packed red blood cells. "In conclusion, our study presents important evidence for the regulation of HAMP expression by Sox2, and this finding can supply a potential therapeutic option to treat anemia of chronic disease." (PMID 25943891, 2015). "We found that Sox2 as a novel factor to bind with HAMP promoter to negatively regulate HAMP expression, which may be further implicated as a therapeutic option for the amelioration of HAMP-overexpression-related diseases, including iron deficiency anemia." (PMID 25943891, 2015).